H19 (H19 imprinted maternally expressed transcript)
Diseases named in the same sentence as H19 in open-access papers (continued):
Sharing a sentence is not in itself a finding about the gene and the disease.
breast cancer (continued). "The interaction of H19 with the EZH2-centered regulation has been previously demonstrated in bladder carcinoma, where a mechanism analogous to the one hypothesized in this paper was proposed, and in ERα-positive breast cancer, contributing to chemoresistance." (PMID 29643989, 2018). "Taken together, these findings suggest that H19, let-7, and Lin28 may form a glucose metabolism-related double-negative feedback loop in breast cancer cells." (PMID 30134946, 2018). "Examples include reports of lncRNA-HOTAIR in ER-induced tamoxifen resistance in breast cancer, lncRNA-UCA1 in cisplatin-based resistance in ovarian cancer cells, LncRNA-AK022798 in cisplatin-based drug resistance in gastric cancer cells and H19 and lncRNA-ROR in hepatocellular carcinoma cells." (PMID 28122578, 2017). "Finally, we show that expression of HMGA1P7 significantly correlates with H19 and IGF2 levels in human breast cancer, suggesting the upregulation of HMGA1P7 may increase H19 and IGF2 expression by a ceRNA mechanism then contributing to cancer progression." (PMID 27874091, 2016). "Furthermore, analyses of H19 and Cbl family gene expression in breast cancer cell lines showed a negative correlation between H19 and c-Cbl or Cbl-b." (PMID 26353930, 2015). "Interestingly, we found that estrogen signaling increased the expression of H19 and ERα but not the well-identified breast cancer targets of estrogen signaling PR and pS2 in matrigel cultures that had been initiated with luminal progenitors." (PMID 25944846, 2015). "In addition, it downregulated the EMT key mediator, Twist1 (as opposed to its high positive correlation with H19 in the murine metastasis model of 4 T1 breast cancer cell line in which Twist was initially identified as a metastasis marker)." (PMID 26536864, 2015). "Although H19 codes for a nontranslated RNA transcript, the H19 product appears to induce growth in lung and breast cancer cell lines and may induce drug resistance in hepato-cellular carcinoma." (PMID 19305507, 2009). "Furthermore, because of the significant correlation of H19, and SPRY4‐IT1 lncRNAs with clinicopathological traits and their excellent power in discriminating breast cancer from healthy individuals, they could be considered as the prognostic biomarkers and novel therapeutic targets in breast cancer." (PMID 36274054, 2023). "Thus, a demonstration of H19 lncRNA function and an identification of H19-CUL4A-ABCB1/MDR1 pathway in chemoresistance have shed new light to the understanding of chemoresistance and will provide new therapeutic targets and strategies for clinical management of breast cancer patients." (PMID 29190892, 2017). "In this study, the expression levels of LincRNA H19, miR-675, MRP3, HOXA1, and MMP16 were consistently higher in 581 breast cancer tissues compared to adjacent non-tumor tissues." (PMID 39267845, 2024). "Triple positive, more differentiated MCF-7 cell line presented higher basal levels of H19 compared to the triple negative, less differentiated and more invasive MDA-MB-231 breast cancer cell line." (PMID 33335214, 2020). "H19 forms a double‐negative circuit with let‐7 and LIN28 in breast cancer cells, wherein H19 sponges the let7 miRNA that consequently releases and promotes the LIN28 expression." (PMID 32146726, 2020). "In order to highlight the role of the H19 gene without ectopic overexpression, the SUM159PT breast cancer cell line was transfected with a vector expressing the stable red fluorescent protein mCherry under the control of the H19 promoter." (PMID 32610610, 2020). "As cancer stem cells tend to cause metastasis in breast tumor, we further examined the expression of H19, LIN28 and let-7 in metastatic and non-metastic mammary tumors from twenty tumor tissues stratified on clinical progression." (PMID 28102845, 2017). "Those lncRNAs include some already known to be involved in cancer, such as H19 and HOTAIR, as well as novel lncRNAs never reported in breast cancer (e.g., HOTAIRM1)." (PMID 25296969, 2014).
breast cancer (continued). "However, no upregulation of lncRNA H19 was observed in MDA-MB-231 resistant cells (Data not shown), which are ERα-negative breast cancer cells." (PMID 27845892, 2016).
gastric cancer (190 papers, 2009 to 2025). A primary or metastatic malignant neoplasm involving the stomach. "The presence of the H19 gene has been associated with an increased risk of colorectal and gastric cancers 16, while polymorphisms in the H19 gene have been shown to influence the incidence of bladder cancer." (PMID 39898248, 2025). "Kaplan–Meier survival estimates showed that high H19 expression in gastric cancer tissues was significantly associated with worse overall survival (p = 0.061, log-rank test)." (PMID 38902391, 2024). "Over-expression of H19 has been confirmed to be associated with anti-apoptotic and metastatic properties in gastric cancer, leading to multi-drug resistance of tumor." (PMID 36246634, 2022). "For instance, H19 rs217727 was found to be associated with oral squamous cell carcinoma, osteosarcoma, bladder cancer, and gastric cancer risk; H19 rs2839698 has been shown to be associated with hepatocellular cancer risk and prognosis." (PMID 34199840, 2021). "The level of H19 in circulation was higher than normal, showing that H19 is a potential diagnostic marker for gastric cancer." (PMID 34670194, 2021). "H19 has been reported to be associated with altered expression of the components of the canonical NF-κB signaling pathway in gastric cancer." (PMID 34977037, 2021). "H19 has been revealed to be associated with the proliferation of gastric cancer cells, and H19 can inhibit the apoptosis of gastric cancer." (PMID 33145980, 2020). "For instance, H19 rs217727 has been reported to significantly increase the risk of gastric cancer, and colorectal cancer." (PMID 31752724, 2019). "H19 has great potential as a promising biomarker due to its high diagnostic value for the detection of gastric cancer (sensitivity 82.9%; specificity 72.9%; AUC 0.838)." (PMID 28634418, 2017). "SNP rs2839698 C>T polymorphism in H19 exon is significantly associated with the increased risk of gastric cancer by altering gene expression levels." (PMID 27626436, 2016). "For example, the dysfunction of lncRNA H19 is associated with various cancers, such as Breast cancer, Lung cancer, Colon cancer, Gastric cancer, Liver cancer, and Bladder cancer." (PMID 27517318, 2016). "One potentially functional H19 single-nucleotide polymorphism (rs217727 C >T) was significantly associated with increased risk of gastric cancer in the Chinese Han population." (PMID 27193186, 2016). "The lncRNA H19 rs217727 polymorphism has been shown to be associated with susceptibility to gastric cancer, breast cancer, and bladder cancer in the Chinese population." (PMID 27486980, 2016). "This case-control study assessed the association between H19 genetic variants and susceptibility to gastric cancer (GC) in a Chinese Han population." (PMID 25944697, 2015). "In summary, we showed that H19 and its associated miR-675 act as oncogenes by promoting cell growth and malignant transformation in human gastric cancer." (PMID 24810858, 2014). "We examined the status of genomic imprinting of the LIT1, IGF2 and H19 genes in 89 gastric cancers by PCR-restriction fragment length polymorphism (RFLP) analysis." (PMID 19737423, 2009). "H19, a well-known lncRNA, has been implicated in gastric cancer promotion." (PMID 41542087, 2025). "Moreover, the diagnostic ability of H19 was high for gastric cancer (GC) (AUC: 0.838) as well as papillary thyroid cancer." (PMID 37373222, 2023). "The upregulated expression of lncRNA H19 in melanoma cells and Helicobacter pylori-induced expression of H19 in gastric cancer cells have been reported to be associated with enhanced cancer cell invasion and migration via activation of the NF-κB- and PI3K/Akt-signalling pathways." (PMID 36899924, 2023).
gastric cancer (continued). "On the contrary, H19 rs217717 was reported to be associated with altered risks of hepatoblastoma, gastric cancer, oral cancer, and lung cancer, while whether the “T” allele is a risk or protective is still controversial." (PMID 33800276, 2021). "For example, the diseases currently known to be associated with H19 are coronary artery disease, gastric cancer, neural tube defects, kidney cancer, infertility, etc., which correspond to cardiovascular, cancer, neurological, renal, and reproduction, respectively." (PMID 33985444, 2021). "Circulating H19 has been explored as a diagnostic and prognostic biomarker for other conditions including coronary artery disease, multiple myeloma, and cancers including bladder and gastric cancer." (PMID 32404103, 2020). "Moreover, H19 gene rs2839698 polymorphism increased the risk of gastric cancer in a Chinese Han population and the rs2839698 CT and TT genotypes were also associated with higher serum H19 mRNA levels." (PMID 32207861, 2020). "LncRNA H19 has been demonstrated as a diagnostic biomarker of gastric cancer with a large range of AUC values (0.6–0.98) in recent studies, which may be correlated with the individual differences." (PMID 32460771, 2020). "Our results revealed that the lncRNA H19 rs2839698 G>A polymorphism might be an important risk factor for developing gastric cancer and colorectal cancer." (PMID 28404885, 2017). "In oncology, Wang and colleagues found that the lncRNA MALAT1 is a biomarker for bladder carcinoma, Xie and his colleagues found that the lncRNA HULC is a biomarker for hepatocellular carcinoma, and Zhou and colleagues found that the lncRNA H19 is a possible diagnostic marker for gastric cancer." (PMID 29463949, 2017). "We next performed an analysis to identify whether H19 or uc001lsz expression was associated with the clinicopathological features of gastric cancer." (PMID 24063685, 2013). "Their faulty expression is also found to cause GC, for example, according to the work done by Song and his team, H19 has high expression in gastric cancer tissues than in normal ones." (PMID 28144288, 2017). "H19 may play an important role in gastric cancer by loss of imprinting and other mechanisms." (PMID 24063685, 2013). "Several lncRNAs, including GAPLIN, GClnc1, HOTAIR, H19 and MEG, have been identified as being strongly associated with gastric cancer." (PMID 40362520, 2025). "In gastric cancer cells, H19 inhibits glucose consumption primarily via the H19/miR-519d-3p/LDHA axis, promotes aerobic glycolysis, proliferation, and regulates immune cell activity, including T cells, Jurkat cells, and TAMs." (PMID 38523627, 2024). "The levels of plasma H19 significantly declined post-surgery in patients with gastric cancer, indicating the potential application of H19 in the early diagnosis and postoperative monitoring settings." (PMID 38688909, 2024). "To identify H19s potentially involved in gastric cancer progression, we analysed H19 expression profiles using the GEPIA II databases." (PMID 38902391, 2024). "The results showed that H19 was overexpressed in gastric cancer tissues compared to adjacent normal tissues." (PMID 38902391, 2024). "H19 has been shown to promote aerobic glycolysis, cell proliferation, and immune escape in gastric cancer cells by acting through the miR-519d-3p/LDHA axis." (PMID 38744310, 2024). "Analysis of H19 expression in gastric cancer patients with different clinicopathological characteristics showed that high or low H19 expression was positively correlated with pathological parameters such as T stage and AJCC stage (all p < 0.05)." (PMID 38902391, 2024). "Mechanistically, H19 regulates the glycolysis of gastric cancer cells to affect cell proliferation through H19/MiR-19a3p /PGK1aix in gastric cancer." (PMID 37821504, 2023).
gastric cancer (continued). "HULC, H19, HOTAIR, and GACAT2 (for “gastric cancer-associated transcript 2”) were found to be significantly increased in the plasma of gastric cancer (GC) patients compared to healthy individuals." (PMID 37190024, 2023). "In preclinical studies, metformin treatment has been shown to inhibit cell migration and invasion by downregulating H19 expression in gastric cancer cells." (PMID 38004379, 2023). "Our research uncovers how aerobic glycolysis and cell proliferation in gastric cancer cells are related to H19." (PMID 37821504, 2023). "Plasma levels of H19 can distinguish gastric cancer patients, even early-stage gastric cancer patients Thus, H19 will be used as a biomarker for the diagnosis of gastric cancer and early cancer screening." (PMID 38933287, 2023). "Another experimental study on gastric cancer illustrated that H19 expression was markedly increased in gastric tumor tissues compared with noncancer tissues." (PMID 36110523, 2022). "The increased level of H19 in gastric cancer tissues and gastric cancer cell lines suggested a main role of H19 in gastric cancer pathology." (PMID 36110523, 2022). "Existing scientific research pointed out that overexpression of H19 promoted gastric cancer cell invasion and migration, while the inhibition of H19 inhibited gastric cancer cell growth." (PMID 36110523, 2022). "After testing 32 blood samples from healthy volunteers with 32 cases of gastric cancer, lncRNA H19 expression levels were significantly higher in patients with gastric cancer and had nothing to do with gender and age." (PMID 35310927, 2022). "Inhibition of H19 expression by siRNA significantly reduced the invasion and migration ability of both malignant gastric cancer cells." (PMID 36246567, 2022). "The expression of H19 in high-grade gastric cancers was significantly higher than that in low-grade gastric cancers." (PMID 36246567, 2022). "It has been reported that an elevated level of H19 is present in gastric cancer and bladder cancer, while the decreased level is present in hepatocellular carcinoma, indicating that H19 has both tumor suppressor as well as oncogenic properties." (PMID 36110523, 2022). "Long non-coding RNAs (lncRNAs) perform a pivotal role in the progression and metastasis of a variety of carcinomas, while lncRNA H19 (H19) is highly prevalent in gastric cancer tissues." (PMID 36611811, 2022). "Our experimental design for the first time depicted that H19 is the upstream member of NF-κB signaling in gastric cancer cells upon TNF-α stimulation." (PMID 36110523, 2022). "The combined analysis of CAI and H19 lncRNA is used to diagnose gastric cancer and their ACC value was further increased to 80.4%." (PMID 35310927, 2022). "Next, we evaluated the effects of H19/miRNA interactions on drug resistance in gastric cancer cells." (PMID 36090894, 2022). "A scientific study on the effect of H19 on gastric cancer showed that the H19 level was significantly elevated in AGS gastric cancer cell line." (PMID 36110523, 2022). "H19 overexpression promotes HP-induced gastric cancer cell proliferation, migration, and invasion by altering the expression of IκBα, phosphorylated IκBα and p65 in the canonical NF-κB signaling pathway." (PMID 34977037, 2021). "A recent paper has shown that H19 and miR-675 increase in gastric cancer, and overexpression of H19 and miR-675 promotes cell proliferation and inhibits apoptosis by downregulation of FADD." (PMID 33499244, 2021).
gastric cancer (continued). "In Helicobacter pylori (HP)-infected gastric cancer tissues and cells, H19 is noteworthily highly expressed." (PMID 34977037, 2021). "From data from The Cancer Genome Atlas (TCGA) databases, high H19 expression gastric cancer patients had a shorter overall survival." (PMID 34977037, 2021). "For instance, lncRNA H19, HOXA11-AS, and SNHG12 were all associated with gastric cancer progression." (PMID 34660323, 2021). "H19 is considered an oncogenic lncRNA that activates oncogenic PI3K/Akt signaling in gastric cancer." (PMID 34977037, 2021). "Based on a new database visualization website of GEPIA with TCGA data and GSE2685 and GSE13861 microarray data from the Gene Expression Omnibus (GEO) databases, H19 is highly expressed in gastric cancer tissue samples." (PMID 34977037, 2021). "Researchers examined H19 expression levels at the in vitro cell level and found that H19 was upregulated in the gastric cancer cell lines AGS, MKN-45, and SGC-7901 compared with the normal gastric mucosa cell line GES-1." (PMID 34977037, 2021). "What is more, the regulatory effects of lncRNA H19 on NF-κB signaling pathway have been excavated in various cancers, such as human osteosarcoma, gastric cancer, melanoma, and glioma." (PMID 33708438, 2021). "miR-675 is processed out of the first exon of H19, and it has been previously reported that H19 and miR-675 expression levels are positively correlated in various cancerous tissues, including gastric cancer, glioma, and colorectal cancer." (PMID 33499244, 2021). "For example, up-regulation of H19 and miR-675 promotes the proliferation of gastric cancer cells and inhibits apoptosis, while knocking down these two genes causes the opposite effect." (PMID 34583640, 2021). "Increasing studies have demonstrated that H19 regulates canonical NF-κB signaling pathway activation in various types of human cancers, such as gastric cancer, thyroid cancer, melanoma, osteosarcoma, and multiple myeloma." (PMID 34977037, 2021). "Taken together, these data demonstrated that H19-derived miR-675 regulated gastric cancer cell progression due to its ability to activate the Akt/mTOR pathway by inhibiting the downregulation of RUNX1." (PMID 34977037, 2021). "In 2016, H19 and LINC00152 levels were evaluated in a Chinese population with H. pylori-associated gastric cancer and it has been shown that lncRNA is a significant cancer biomarker." (PMID 34337048, 2021). "A study of gastric carcinoma showed that activation of the H19‐miR‐29a‐3p‐COL1A2 axis was positively correlated with M2 macrophage infiltration." (PMID 34598322, 2021). "H19 is overexpressed in both gastric cancer and gastric cancer cell lines, and the same trend can be observed in plasma." (PMID 32695786, 2020). "H19, a gene product playing a role in imprinting, promotes gastric cancer metastasis by regulating c‐Myc." (PMID 33145980, 2020). "Specifically, curcumin inhibited cell proliferation via c-Myc/H19 pathway, which reduced the expression of H19 in stomach cancer cells." (PMID 33680956, 2020). "In many recent studies, H19 was identified as an onco-lncRNA and to promote tumorigenesis, such as in glioblastoma, colorectal cancer, and gastric cancer." (PMID 32978516, 2020). "Previous studies have shown that H19 is upregulated in gastric cancer and that it is significantly correlated with poor prognosis of gastric cancer patients." (PMID 33333725, 2020).